CAV1 (caveolin 1)
Diseases named in the same sentence as CAV1 in open-access papers (continued):
Sharing a sentence is not in itself a finding about the gene and the disease.
pancreatic cancer (continued). "A connection between Cav1 and the DNA repair process has been demonstrated, given that silencing of Cav1 increased the levels of residual DNA double-strand breaks in irradiated 3D cell cultures, and Cav1 knockdown sensitized pancreatic tumour cell lines grown in 3D lrECM to X-rays." (PMID 23521716, 2013). "Thus, caveolin-1 might cooperate with other molecules, such as c-Src and Grb7, to stimulate tumour growth in pancreatic carcinoma." (PMID 12402154, 2002). "However, at present, the role of caveolin-1 in pancreatic carcinoma remains unclear, and elucidation awaits further investigation." (PMID 12402154, 2002). "The clinical effects of caveolin-1 expression in pancreatic carcinoma, however, remain unknown." (PMID 12402154, 2002). "Direct binding of KLF4 to the promoter region of caveolin-1 and reduced the level of caveolin-1 to inhibit EMT and metastasis in pancreatic cancer." (PMID 35768405, 2022). "As CAV1 mediates caveola-mediated exocytosis, CAV1 stabilization enhances LIF exocytosis from CAFs and activates the JAK–STAT signaling pathway in pancreatic cancer cells." (PMID 36467402, 2022). "Supporting these in vitro observations, in pancreatic cancer samples, KLF4 correlated positively with E-cadherin and negatively with vimentin and Cav-1, a direct transcriptional target of KLF4 that can inhibit EMT in pancreatic cancer." (PMID 34680284, 2021). "CM from sh-Cav-1 PSCs exhibited upregulated levels of shh, MMP2, bFGF, and IL-6, which exert proliferative, invasive, angiogenic, and inflammatory functions during pancreatic cancer progression." (PMID 32377291, 2020). "Thus, Cav-1 expression in pancreatic cancer may be important for the prognosis of this disease." (PMID 26065715, 2015). "Cav-1 fluorescence signal in CAFs was lower than that in PAF and NF specimens, which suggests that Cav-1 is lost in a pancreatic cancer microenvironment." (PMID 24949874, 2014). "Previous studies indicated that caveolin-1 is a crucial modulator of EMT and cell differentiation in pancreatic cancer cells." (PMID 24520289, 2014). "Pancreatic cancer cells transfected with miR-375 showed the down-regulation of insulin-like growth factor-binding protein-5 (IGFBP5) and caveolin-1 (CAV1), and BITC possibly targeted the up-regulation of IGFBP5 and CAV-1 through suppressing the expression of miR-221 and miR-375." (PMID 36765652, 2023). "On this basis, we assumed that the lack of Cav-1 in PSCs would accelerate the growth of pancreatic cancer cells through paracrine signaling." (PMID 32377291, 2020). "Interestingly, ACAT1 inhibition has been reported to promote downregulation of the CAV1/MAPK pathway, which enhances pancreatic cancer aggressivity." (PMID 32458269, 2020). "Cav-1 silencing increased chemosensitivity or radiosensitivity in diverse cancer cells such as Ewing's sarcoma cells A4573, Madin-Darby canine kidney cells MDCKII and the pancreatic cancer cell line MiaPaCa2." (PMID 26431273, 2015). "The absence of caveolin-1 expression was sufficient to promote pancreatic cancer cell migration and invasion." (PMID 24520289, 2014). "It is possible that biphasic expression of cav-1; meaning, overexpression in primary tumors and low or absent expression in metastases occurs in pancreatic cancer." (PMID 15969750, 2005). "In the present study, positive caveolin-1 expression was detected in 32 out of 79 tumours (40.5%) in pancreatic carcinoma, while non-neoplastic ductal epithelium showed little or no immunoreactivity." (PMID 12402154, 2002). "In pancreatic cancer, the role of Cav-1 is not well-defined." (PMID 26065715, 2015). "Other work suggested that Cav-1 expression was significantly correlated to tumor diameter, histological grade and poor prognosis in pancreatic cancer, and indicated that Cav-1 might be an independent negative predictor of survival." (PMID 26431273, 2015).
pancreatic cancer (continued). "In summary, overexpression of caveolin-1 in pancreatic carcinoma may contribute to tumour progression and be a negative prognostic predictor following surgery." (PMID 12402154, 2002).
pulmonary hypertension (65 papers, 2009 to 2026). Increased pressure within the pulmonary circulation due to lung or heart disorder. "In pulmonary hypertension, the dysregulation of Cav-1 contributes to abnormal vascular remodeling and increased pulmonary artery pressure, with a noted association between Cav-1 loss and disease progression." (PMID 40497951, 2025). "Interaction with Cav-1, however, avoids excessive or aberrant eNOS activity, and Cav-1 deficiency can cause pulmonary hypertension and cardiomyopathy." (PMID 39917079, 2025). "In knockout mice, the loss of caveolin-1 gives rise to abnormal circulatory and pulmonary functions, and reduced expression of caveolin-1 is also associated with malignancy, fibrosis, and pulmonary hypertension." (PMID 39769167, 2024). "Numerous studies have examined that caveolin-1 is closely associated with the development of various diseases, including pulmonary hypertension, vascular abnormalities, metabolic diseases, and cancer." (PMID 37576808, 2023). "In mice, loss of caveolin-1 resulted in vascular abnormalities and pulmonary hypertension, which were associated with damaged caveolae structure." (PMID 37298580, 2023). "To further test this model, we analyzed CAV1 P158PfsX22, a frameshift mutation associated with pulmonary arterial hypertension." (PMID 37526691, 2023). "Christy Moore reported that consistent with the effect of knockout of Cav1, CAV1 gene mutation was molecularly similar to drive metabolic deficiencies, pulmonary hypertension, and reduced spontaneous exercise in mice." (PMID 36147736, 2022). "Although animal and human studies suggest that aberrations in Caveolin1 (CAV1) signaling participate in the development of pulmonary vascular disorders, limited reports of CAV1‐associated heritable pulmonary arterial hypertension (HPAH) exist." (PMID 35864912, 2022). "Activation of the proliferative and anti-apoptotic pathways, due to the loss of the inhibitory function of endothelial caveolin-1, leads to vascular remodeling and pulmonary hypertension." (PMID 32257548, 2020). "Hypoxia is a standard “second hit” for pulmonary hypertension genetic models, and Cav1 has previously been extensively associated with vasoreactivity, particularly through nitric oxide." (PMID 33015095, 2020). "Other examples include a F160X Cav1 frame shift mutation associated with both pulmonary arterial hypertension (PAH) and congenital generalized lipodystrophy that causes premature truncation of the protein." (PMID 33015095, 2020). "Recent studies also have revealed that Cav-1 was associated with pulmonary arterial hypertension and was upregulated in high-salt diet-induced endothelial dysfunction and hypertension in type 1 diabetes." (PMID 27119011, 2016). "Emerging evidence suggests that caveolin-1 (Cav1) is associated with pulmonary arterial hypertension." (PMID 27546070, 2016). "Cav1 is widely expressed, and genetic loss of Cav1 in mice results in almost complete loss of caveolae in vivo, associated with altered lipid metabolism, pulmonary hypertension and fibrosis, nitric oxide (NO) dysfunction, and cardiac abnormalities." (PMID 25550395, 2015). "In this study, we investigated a young patient with a heterozygous CAV1 mutation who presented with a progeroid appearance, lipodystrophy and pulmonary hypertension." (PMID 26176221, 2015). "Altogether, the data discussed in this chapter also strongly suggest that loss of Cav-1 in ECs is primary responsible for the pulmonary hypertension observed in Cav-1 KO mice and in humans." (PMID 26605130, 2012). "Both humans and Cav-1 deficient mice are noted to develop pulmonary hypertension as a result of uncontrolled eNOS activation due to a lack of Cav-1." (PMID 22934034, 2012). "Because eNOS is robustly expressed in the plexiform lesions of idiopathic pulmonary arterial hypertension lungs, these data support the idea that eNOS hyperactivation due to loss of Cav-1 is important in developing pulmonary hypertension in mice and humans." (PMID 26605130, 2012).
pulmonary hypertension (continued). "Strikingly, several other disease-associated mutations in CAV1 identified in patients with pulmonary arterial hypertension and/or lipodystrophy syndromes cluster near the residues P158 and F160 in the structure, whereas another set of mutations are located in the scaffolding domain." (PMID 37082988, 2023). "Mutations in CAV1 are also linked to pulmonary arterial hypertension and lipodystrophies." (PMID 37082988, 2023). "However, inflammatory and metabolic defect-associated pulmonary arterial hypertension were observed in the expression of a human caveolin-1 mutation in mice." (PMID 36559147, 2022). "However, in 2012, Cav1 mutations were found as the likely causative mutations in a familial pulmonary hypertension family, and since then, causative mutations have been found in additional families, although it remains a rare cause." (PMID 33015095, 2020). "Additionally, Cav1-deficient mice exhibit pulmonary hypertension, impairment of left ventricular diastolic function, increased pulmonary vascular remodeling, and right ventricle hypertrophy and decreased contractility." (PMID 33519523, 2020). "Additionally, Cav-1 is linked to hypoxia-derived pulmonary hypertension and vascular remodeling mediated by PY-STAT3." (PMID 31736773, 2019). "Interestingly, as previously discussed for Cav-1, the same EC-specific hyperproliferative phenotype observed in Cav-1 KO mice has been implicated in specific diseases such as pulmonary hypertension." (PMID 26605130, 2012). "Also, clinical evidence supports the importance of endothelial Cav-1 deficiency in development of pulmonary hypertension in patients." (PMID 26605130, 2012). "Downregulation of Cavin-1 ameliorated CAV1 knockdown-induced pulmonary hypertension by recovering Smad 1/5/9 phosphorylation in PAECs." (PMID 38182755, 2024). "Cavin-1 knockdown reversed pulmonary hypertension and vascular remodeling induced by CAV1 knockdown." (PMID 38182755, 2024). "CAV1−/− mice developed pulmonary hypertension under normoxic conditions with elevated pressure in the right ventricle, right ventricular hypertrophy, and pulmonary vascular remodeling." (PMID 38182755, 2024). "Reduced Caveolin-1 expression was found in the vessels of COPD patients with pulmonary hypertension." (PMID 36819141, 2023). "Cav1 participation in vascular function and smooth muscle contraction is further demonstrated by the development of pulmonary hypertension and right-ventricular hypertrophy seen in Cav1 knockout mice." (PMID 37998001, 2023). "The disruption of endothelial caveolin-1 (Cav1), a cell membrane protein, has been shown to play a key role in the initiation and progression of pulmonary hypertension (PH) in experimental models, and also in human PAH." (PMID 37367058, 2023). "These defects lead to disease conditions such as pulmonary arterial hypertension and congenital generalized lipodystrophy in the case of CAV1 mutants or sarcolemma damage and muscular dystrophies for CAV3 mutants." (PMID 37526691, 2023). "Caveolin-1 has been stated to be related to pulmonary arterial hypertension, coronary artery disease, and MMA." (PMID 37273690, 2023). "In pulmonary arterial hypertension (PAH), when mutations in the last 21 amino acids of Cav-1 are replaced with a novel 22-amino-acid sequence, an inflammatory challenge [low-dose lipopolysaccharide (LPS)] leads to metabolic deficiencies and mild pulmonary hypertension in mouse models." (PMID 36559147, 2022). "Cav1−/− mice develop pulmonary hypertension with increased oxidative stress and impaired endothelial function." (PMID 34068984, 2021). "Several mutations that decrease caveolin-1 (CAV1) expression were found in PAH, and CAV1 knock-out in animal models leads to pulmonary hypertension." (PMID 34346486, 2021). "Deletion of Cav‐1 in mice also developed pulmonary hypertension, myocardial hypertrophy, and alveolar cell hyperproliferation through the activation of p42/44 MAP kinases." (PMID 32508059, 2020).
pulmonary hypertension (continued). "Their results suggested that increased expression of caveolin-1 in the aorta of pulmonary hypertensive rats affects the function of receptor-operated Ca2+ channels; this represents a mechanism of pulmonary vascular smooth muscle remodeling." (PMID 32257548, 2020). "The expression of Cav‐1 was downregulated in peripheral monocytes or plasma harvested from patients with asthma or COPD along with pulmonary hypertension." (PMID 32508059, 2020). "There was an extensive literature on Cav1 knockout driving pulmonary hypertension in mice, but this was largely theoretical since it had not been seen in humans." (PMID 33015095, 2020). "Collectively, the different roles of caveolin-1 in pulmonary hypertension partly depend on the function of supporting cells." (PMID 32257548, 2020). "During pulmonary hypertension, in contrast to the activity of caveolin-1 in endothelial cells, the expression of caveolin-1 is increased and Ca2+ regulation is altered in vascular smooth muscle cells." (PMID 32257548, 2020). "Increased Cav‐1 expression in pulmonary arterial hypertension enhanced agonist‐induced contraction via modulation of receptor‐operated calcium channels and store‐operated calcium channels in pulmonary arteries, playing a vital role in disease pathology." (PMID 32508059, 2020). "In opposition, inCav1–/– mice, cardiomyopathy was shown to be secondary to Cav1 deletion and pulmonary hypertension." (PMID 31656583, 2019). "Cav1-null (Cav1−/−) mice exhibit hypertrophy and dilatation of both ventricles, pulmonary hypertension, and metabolic disorder." (PMID 27612189, 2016). "Cav1-/- knockout mice show progressive lipodystrophy, insulin resistance and pulmonary hypertension and characteristics of dilated cardiomyopathy." (PMID 26176221, 2015). "Caveolin-1 null mice display a marked reduction in life span due to a combination of cardiac hypertrophy, pulmonary fibrosis and pulmonary hypertension." (PMID 25324780, 2014). "Mutations in the caveolin-1 gene and decreased expression of caveolin-1 have been identified in patients with pulmonary arterial hypertension, a disease with high morbidity." (PMID 25324780, 2014). "This notion is further supported by the fact that pulmonary hypertension was completely reversed in Cav-1 KO mice by a specific re-expression of Cav-1 in endothelium." (PMID 26605130, 2012). "For instance, Cav1 reduction can be seen in rat models of pulmonary hypertension including monocrotaline-induced pulmonary hypertension and U5416/hypoxia-induced pulmonary hypertension." (PMID 26605130, 2012). "Remarkably, specific loss of Cav-1 in ECs appears to be responsible for many of pathologies reported in Cav-1 KO including pulmonary hypertension and cardiac hypertrophy." (PMID 26605130, 2012). "The expression of CAV1 was also decreased in monocrotaline-induced pulmonary hypertension." (PMID 36038916, 2022). "Importantly, CAV1 was reported to be associated not only with MMD, but also with coronary artery disease and pulmonary artery hypertension." (PMID 34381413, 2021). "The function of CAV1 is well-characterized in pulmonary artery hypertension." (PMID 34381413, 2021). "Even the homozygous mice in the present study had less of a pulmonary hypertensive phenotype than had previously been published for Cav1 knockouts, although the level of pulmonary hypertension in other studies has also been variable, with some studies showing no increased pressure at baseline." (PMID 33015095, 2020). "Indeed, selective restoration of Cav1 expression in endothelial cells completely rescued pulmonary hypertension and cardiac hypertrophy inCav1–/– mice." (PMID 31656583, 2019). "Thus, the absence of caveolin-1 (Cav1)-mediated negative regulation of eNOS in Cav1−/− mice results in over-activation of eNOS and increased protein nitration in lungs and development of severe pulmonary hypertension." (PMID 31100969, 2019). "Cav1−/− mice exhibit pulmonary hypertension and right ventricle hypertrophy." (PMID 26539466, 2015).